TFE3 (transcription factor binding to IGHM enhancer 3)
Diseases named in the same sentence as TFE3 in open-access papers (continued):
Sharing a sentence is not in itself a finding about the gene and the disease.
fibroma (2 papers, 2023). A non-metastasizing neoplasm arising from the fibrous tissue. "In our study, seven out of eight SST cases expressed luteinized cells with moderate-to-strong staining of TFE3, but it was negative in the ovarian granulosa, microcystic stromal tumor and thecoma/fibroma." (PMID 37528481, 2023). "Of the nine fibromas/thecomas, TFE3 was weakly staining in 2 cases and negative in the remaining 7 cases." (PMID 37528481, 2023). "TFE3 overexpression has been reported in 78% of SSTs, especially in epithelioid/luteinized cells, while thecomas and fibromas do not express TFE3." (PMID 38136408, 2023).
glioma (2 papers, 2021 to 2022). A benign or malignant brain and spinal cord tumor that arises from glial cells (astrocytes, oligodendrocytes, ependymal cells). "Based on the TCGA and GTEx database, we obtained that TFE3 was specifically overexpressed in gliomas among different cancers." (PMID 35269968, 2022). "The results confirmed it was specific that TFE3 mediated HOXD-AS2 in gliomas." (PMID 35269968, 2022). "The data above demonstrated that HOXD-AS2 was induced by TFE3 and H3K27ac in glioma cells." (PMID 35269968, 2022). "The expression of TFE3 was lower in gliomas with 1p19q co-deletion." (PMID 35269968, 2022). "Furthermore, we found that the high expression of TFE3 in glioma was also specific and the level of H3K27ac upstream of HOXD-AS2 was low in astrocyte cells." (PMID 35269968, 2022). "The results demonstrated that the expression of c-Myc, cyclin D1, cyclin A, and E2F1 decreased after knocking down TFE3, suggesting that the TFE3-mediated overexpression of HOXD-AS2 promoted the cell cycle progression in glioma cells." (PMID 35269968, 2022). "In summary, our work revealed the mechanism that TFE3 and miR-661 specially regulated HOXD-AS2 in glioma overexpression, and we hope that this work will pave the way for exploring gene specific expression." (PMID 35269968, 2022). "In the future, we may be able to explore whether TFE3 and the TGF-β signaling pathway are related with regulating HOXD-AS2 expression in gliomas." (PMID 35269968, 2022). "We did not study how TFE3 recruited H3K27ac in gliomas, which could be a direction for future exploration." (PMID 35269968, 2022).
granulosa cell tumor (2 papers, 2022 to 2023). A slow-growing, malignant tumor, characterize by the presence of granulosa-like cells and Call-Exner bodies, that is almost always found in the ovary. "TFE3 was not expressed in 20 cases of granulosa cell tumors (20/20)." (PMID 37528481, 2023).
Hypoglycemia (2 papers, 2023 to 2025). A decreased concentration of glucose in the blood. "Surprisingly, however, TFEB/TFE3‐deficient mice, despite showing a massive increase in INS mRNA levels, do not show hypoglycemia but instead are glucose intolerant, suggesting that lack of TFEB and TFE3 may affect β‐cell function and insulin production at different levels." (PMID 37712288, 2023).
liposarcoma (2 papers, 2020 to 2022). A usually painless malignant tumor that arises from adipose tissue. "Two samples displayed weak signals for TFE3 in dedifferentiated liposarcoma among control tumours, and 88% of SFT samples showed a strong presence of TFE3 indicating that TFE3 can act as a potential marker for the diagnosis of SFT." (PMID 32566457, 2020). "Two cases (n = 2) of dedifferentiated liposarcoma were moderately positive for nuclear TFE3 (2+)." (PMID 32566457, 2020).
osteopetrosis (2 papers, 2020 to 2021). Osteopetrosis, also known as marble bone disease, is a descriptive term that refers to a group of rare, heritable disorders of the skeleton characterized by increased bone density on radiographs. "Redundancy between MITF and TFE3 was also suggested by the observation that loss of function mutation in either gene leads to normal bone development whereas simultaneous knockout of both factors resulted in the development of severe osteopetrosis in mice." (PMID 32881934, 2020). "The MiTF/TFE3 redundancy establishes a critical role for the MiT family in osteoclastogenesis and provides an interpretation of why osteopetrosis in humans has not been related to MiTF genetic alterations." (PMID 33441180, 2021).
papillary carcinoma (2 papers, 2021 to 2022). A malignant epithelial neoplasm characterized by a papillary growth pattern. "However, little is known about its role in papillary thyroid carcinoma (PTC) or the potentially oncogenic role of TFE3 in regulating the autophagy-lysosome system." (PMID 34660181, 2021).
steatosis (2 papers, 2016 to 2021). Increased lipid within the cytoplasm of cells. "It is of great interest that steatosis was observed upon hepatic ablation of TFE3 while hepatic overexpression of TFE3 resulted in a decrease of steatosis via lipophagy induction." (PMID 34777688, 2021). "In the present study, we show that over-expression of TFE3 ameliorates the steatosis in hepatocytes exposed to free fatty acids (FFAs)." (PMID 26999124, 2016). "On the contrary, downregulation of TFE3 resulted in an aggravated steatosis." (PMID 26999124, 2016). "As a result of these changes, TFE3 attenuates FFA-induced intracellular steatosis in hepatocytes." (PMID 26999124, 2016).
tongue squamous cell carcinoma (2 papers, 2019 to 2021). A squamous cell carcinoma that arises from the tongue. "Furthermore, recently evidence has shown that melatonin-induced apoptosis enhances the antitumor effect in tongue squamous cell carcinoma (TSCC) through the inhibition of melatonin receptor type 2 (MT2) -Transcription Factor E3 (TFE3)-dependent autophagy." (PMID 31684096, 2019).
adenoid cystic carcinoma (1 paper, 2014). A malignant tumor arising from the epithelial cells. "In the present study, we explored the expression and correlation of survivin with HIF-1α, TGF-β1 and TFE3 in adenoid cystic carcinoma (AdCC)." (PMID 25485635, 2014).
Atrophy (1 paper, 2024). Any weakening or degeneration, especially through lack of use. "The role of lysosomes and TFE3 are poorly understood in muscle atrophy, and the effect of biological sex is widely underreported." (PMID 38643162, 2024). "However, TFE3 appears to be more critical in the lysosomal and autophagy responses in females, indicating a sexually dimorphic function of TFE3 in response to denervation-induced muscle atrophy of this relatively short-term duration." (PMID 38643162, 2024).
benign peripheral nerve sheath tumor (1 paper, 2019). "Neurofibromas are benign peripheral nerve sheath tumors, and none of our studied neurofibroma samples (0/4) were stained positive for TFE3." (PMID 31043173, 2019).
brain tumors (1 paper, 2024). "Working in vivo, multiple studies demonstrated that several YAP fusion proteins, such as YAP::FAM118B, YAP::MAML2, YAP::MAMLD1, YAP::SS18, and YAP::TFE3, can induce brain tumors and/or muscle tumors in mice." (PMID 40491864, 2024). "In vivo, mutation of the TEAD binding site of YAP in YAP::MAML2, YAP::MAMLD1, YAP::FAM118B, YAP::SS18, and YAP::TFE3 significantly reduced the oncogenic potential of these protein fusions to initiate brain tumors in mice." (PMID 40491864, 2024). "Mouse brain tumors formed from YAP::FAM118B, YAP::MAMLD1, or YAP::SS18 fusion protein expression showed distinct morphology and gene expressions profiles from brain tumors with the YAP::TFE3 fusion protein." (PMID 40491864, 2024).
breast tumor (1 paper, 2022). "Thus, FLCN loss appears to induce TFE3-dependent breast tumor growth through activation of multiple mechanisms that reveal a general role of a deregulated FLCN/AMPK/TFE3 pathway in human cancers." (PMID 35070081, 2022).
Central hypothyroidism (1 paper, 2023). A type of hypothyroidism due to an insufficient stimulation of an otherwise normal thyroid gland. "FAM47A and TFE3 were potential risk genes for hypertension, whereas IRS4, an insulin signaling-pathway gene associated with central hypothyroidism, potentially linked with cardiac defects." (PMID 37800145, 2023).
chondroid syringoma (1 paper, 2022). "In a previous report, a malignant chondroid syringoma (MCS) demonstrated PHF1-TFE3 gene fusion and strong TFE3 immunohistochemical (IHC) staining." (PMID 35225876, 2022). "In this study, we used TFE3 IHC stain to detect possible gene fusions in chondroid syringomas (CSs)." (PMID 35225876, 2022). "Recently, a new gene fusion of plant homeodomain (PHD) finger protein 1 gene (PHF1) to TFE3 was identified in a malignant chondroid syringoma." (PMID 35225876, 2022). "Materials: Eleven benign chondroid syringoma (BCS), one atypical chondroid syringoma (ACS), and one malignant chondroid syringoma cases were identified, stained with TFE3 IHC stain, and interpreted based on preset criteria." (PMID 35225876, 2022). "Based on this finding, the authors postulated that there might be a genetic link between malignant chondroid syringomas and PHF1 or TFE3 altered tumors." (PMID 35225876, 2022).
ductal adenocarcinomas (1 paper, 2020). "A combined IHC panel of beta catenin, LEF1 and TFE3 resulted in a sensitivity and specificity of 100 and 91.9% in distinguishing SPNs from ductal adenocarcinomas and Pan NETs." (PMID 33298094, 2020). "On the other hand, about 15 to 25% Pan NETs, ductal adenocarcinomas and pancreatic neuroendocrine carcinomas respectively show positivity for TFE3." (PMID 33298094, 2020).
eosinophilia (1 paper, 2021). "If TFE3/TFEB are drivers of TSC-RCC, this might explain some of the histologic phenotypes of TSC-RCC, including the eosinophilia, since TFE3/TFEB promote mitochondrial biogenesis." (PMID 34680979, 2021).
gastrointestinal stromal tumor (1 paper, 2019). "The distribution rates of TFE3 positivity in nodular fasciitis, gastrointestinal stromal tumor, leiomyoma and scar tissue samples were 42.9, 40, 25 and 33%, respectively." (PMID 31043173, 2019).
hepatic (1 paper, 2025). "While the prognosis difference between the TFE3-subtype and CAMTA1-subtype hepatic EHE still needs to be further explored in a larger study cohort." (PMID 40040722, 2025).
HIV encephalitis (1 paper, 2021). "For example, the gene TFE3 is implicated in HIV encephalitis." (PMID 33546175, 2021).
hypercholesterolaemia (1 paper, 2017). "Tfe3 KO mice showed hyperleptinaemia, hypoadiponectinaemia, hyperinsulinaemia and hypercholesterolaemia compared to controls (Fig EV3B)." (PMID 28283651, 2017).
leiomyoma (1 paper, 2019). A well-circumscribed benign smooth muscle neoplasm characterized by the presence of spindle cells with cigar-shaped nuclei, interlacing fascicles, and a whorled pattern. "Likewise, 0/3 leiomyoma samples were TFE3 positive, and the same trend (0/2) was observed for intermediate type myofibroblastic tumors." (PMID 31043173, 2019).
leiomyosarcoma (1 paper, 2020). An uncommon, aggressive malignant smooth muscle neoplasm, usually occurring in post-menopausal women. "In difficult cases, immunolabeling for more than one melanocytic marker and the demonstration of TSC2 mutations/alterations or TFE3 translocations might be helpful to differentiate PEComa from aberrant HMB-45-positive leiomyosarcoma." (PMID 31309284, 2020).
lipomatosis (1 paper, 2023). A neoplastic process characterized by diffuse overgrowth of mature adipose tissue. "The lipomatosis could be either a direct effect of the PRDM10 variant, for example by gene expression changes other than FLCN reduction, or it may be an adipose tissue-specific effect of folliculin repression and downstream TFE3/TFEB activation, which is described to play a role in adipose tissue." (PMID 36440963, 2023).
liver cancer (1 paper, 2025). An epithelial or non-epithelial malignant neoplasm that arises from the liver. "Notably, depletion of TFE3, but not TFEB, in the liver of FlcnLiKO mice fully rescues the cancer phenotype and normalized mTORC1 signaling, highlighting TFE3 as the primary driver of liver cancer and mTORC1 hyperactivity in the absence of FLCN." (PMID 40189703, 2025).
liver disease (1 paper, 2021). "In this aggressive liver disease setting, loss of Flcn led to activation of transcription factors TFEB and TFE3 to promote autophagy, promoting the degradation of intracellular lipid stores, ultimately resulting in reduced hepatocellular damage and inflammation." (PMID 34711912, 2021).
liver fibrosis (1 paper, 2025). "In addition, deletion of TFE3 in F3KO led to a reduction in liver fibrosis, a decrease in SOX9 expression in hepatocytes, and normalization of mTORC1 activity, as demonstrated by P-S6 immunostaining and immunoblot for P-4EBP1." (PMID 40189703, 2025).
lung adenocarcinoma (1 paper, 2020). A carcinoma that arises from the lung and is characterized by the presence of malignant glandular epithelial cells. "Accordingly, we detect partial constitutive localization of TFE3 in the nucleus of HeLa and lung adenocarcinoma cells." (PMID 32686708, 2020).
memory impairment (1 paper, 2023). "Our findings suggest that TNEA attenuates AD-associated memory impairment via promoting TFEB/TFE3-mediated autophagic clearance of Aβ and NLRP3 inflammasome, and partially reveal the molecular basis of combined acupoints therapy originated from ancient wisdom." (PMID 36732771, 2023).
metastatic melanoma (1 paper, 2019). A melanoma that has spread from its primary site to another anatomic site. "In metastatic melanomas TFEB and TFE3 positively correlate with the expression of genes required for the immune response." (PMID 30705290, 2019).
neoplasm of the bile ducts (1 paper, 2025). "The regions showing neoplasm of the bile ducts showed nuclear TFEB, TFE3, and SOX9, and hyperactivation of mTORC1 as evidenced by immunostaining for the phosphorylated S6 protein of the 40S ribosomal subunit (P-S6), used as readout of mTORC1 activity." (PMID 40189703, 2025).
neurothekeoma (1 paper, 2025). A benign neoplasm arising from nerve sheaths. "Aberrant expression of TFE3, a transcription factor involved in lysosomal biogenesis and immune response, has been reported in a case series, indicating its potential role in the pathogenesis of cellular neurothekeoma." (PMID 40538780, 2025).
ovarian granulosa cell tumor (1 paper, 2023). A granulosa-stromal cell tumor that arises from the ovary. "TFE3 was expressed mainly in sclerosing stromal tumors but not in ovarian granulosa cell tumors, thecoma, or microcystic stromal tumors." (PMID 37528481, 2023).
pediatric renal cell carcinoma (1 paper, 2011). "Notably, two other members of the MiT family of basic-helix-loop-helix/leucine zipper transcription factors, TFE3 and TFEB, have been recurrently affected by translocations that result in the upregulation of these transcription factors in human pediatric renal cell carcinoma." (PMID 22039523, 2011).
polyp (1 paper, 2024). A usually exophytic mass attached to the underlying tissue by a broad base or a thin stalk.
Pompe disease (1 paper, 2014). "The regulation of TFEB and TFE3 in skeletal muscle in general and in Pompe disease in particular remains an open question." (PMID 25183957, 2014).
rectal cancer (1 paper, 2019). A primary or metastatic malignant neoplasm that affects the rectum. "We report an intriguing case of TFE3-expressing primary PEComa of the LN mimicking nodal recurrence of rectal cancer as suggested by imaging data." (PMID 31103952, 2019). "We report a rare case of TFE3-expressing primary LN PEComa that mimicked nodal recurrence of rectal cancer." (PMID 31103952, 2019). "We herein report an illustrative case of TFE3-expressing primary PEComa of a lymph node (LN) in the gastrosplenic area that mimicked nodal relapse from rectal cancer as suggested by imaging." (PMID 31103952, 2019).
spindle-cell tumor (1 paper, 2014). "Histological analysis of the 68 specimens revealed 61 clear cell tumors, three papillary tumors, one chromophobe tumor, one spindle-cell tumor, one myogenic tumor and one tumor related to Xp11.2 translocation/TFE3 gene fusion." (PMID 24902995, 2014).
ZIKV infections (1 paper, 2021). "In this work, evidence obtained in three different cell lines, from vertebrate and mosquito origin, is presented indicating that DENV and ZIKV infections triggers the Golgi stress response and the activation of the TFE3 pathway in infected vertebrate cells." (PMID 34873243, 2021). "Thus, to address if the observed activation of the Golgi stress response was specific for DENV and ZIKV infections, CRFK cells infected with FCV were analyzed for Golgi expansion or translocation of the TFE3 factor." (PMID 34873243, 2021).